RNU6-580P (RNA, U6 small nuclear 580, pseudogene)
Gene: Small nuclear RNA gene on chromosome 2 (159,027,036 to 159,027,142, reverse strand). Ensembl gene ENSG00000202029.
Homologues: Orthologues: chimpanzee U6 (100% identical), macaque U6 (93% identical), dog U6 (79% identical), rat LOC120101201 (72% identical), mouse Gm23955 (71% identical), guinea pig U6 (69% identical). Paralogues in human: RNU6-345P (87% identical), RNU6-83P (87% identical), RNU6-86P (87% identical), RNU6-116P (86% identical), RNU6-1175P (86% identical), RNU6-11P (86% identical), RNU6-1209P (86% identical), RNU6-188P (86% identical), RNU6-28P (86% identical), RNU6-37P (86% identical), RNU6-698P (86% identical), RNU6-742P (86% identical), and 1284 more.